CCND1 (cyclin D1)
Diseases named in the same sentence as CCND1 in open-access papers (continued):
Sharing a sentence is not in itself a finding about the gene and the disease.
Down syndrome (4 papers, 2015 to 2021). "Moreover, radial glial progenitors in the Ts65Dn mouse model of Down syndrome have less Cyclin D1, and Dyrk1a is the triplicated gene that causes both early cortical neurogenic defects and decreased nuclear Cyclin D1 levels in this model." (PMID 26137553, 2015). "In Down syndrome, increased DYRK1A expression increases G1 cell cycle duration through phosphorylation and degradation of cyclin D1." (PMID 34708541, 2021).
Familial adenomatous polyposis (4 papers, 2013 to 2022). Familial adenomatous polyposis (FAP) is characterized by the development of hundreds to thousands of adenomas in the rectum and colon during the second decade of life. "Berberine reduced the expression of Wnt-target genes Cyclin D1 and c-Myc in mice, in addition to decreasing the recurrence of polyps in seven patients with familial adenomatous polyposis by reducing Cyclin D1 expression." (PMID 35053565, 2022). "In clinical practice, oral administration of berberine also significantly reduced the familial adenomatous polyposis patients' polyp size along with the inhibition of cyclin D1 expression in polyp samples." (PMID 24015932, 2013). "Over-expression of cyclin D1 and CDK4 were evident in the majority of human intestinal adenoma of familial adenomatous polyposis." (PMID 26416244, 2015).
HCMV infection (4 papers, 2012 to 2017). "Whereas Cyclin D1 expression was largely unaffected by HCMV infection and all four viruses led to a strong and sustained induction of Cyclin E1, they markedly differed with respect to Cyclin A2, Cyclin B1 and APC5 protein regulation." (PMID 25393019, 2014). "We found that HCMV infection enhanced the expression of cyclin D1 in HepG2 cells." (PMID 23555719, 2013).
Hypercalcemia (4 papers, 2011 to 2025). An abnormally increased calcium concentration in the blood. "Cyclin D1 positivity was significantly associated with hypercalcemia." (PMID 37250623, 2023). "Hypercalcemia was significantly associated with the expression of cyclin D1 (p = 0.042)." (PMID 37250623, 2023).
Hypoglycemia (4 papers, 2016 to 2025). A decreased concentration of glucose in the blood. "Western blotting results showed that hypoglycemia and euglycemic conditions induced a decrease in protein expression of cyclin D1 and MCL-1 in both cells." (PMID 26959121, 2016). "Post-PH hypoglycemia can promote Cyclin D1 expression to induce early G1 progression." (PMID 39920130, 2025). "Subsequent to this finding, Daniel Chung and colleagues overexpressed cyclin D1 in murine islets in vivo and showed an exceptional increase in islet mass without hypoglycemia, proposing β-cell replication as the cause of the islet hyperplasia." (PMID 26759123, 2016). "Interestingly, the β-cell-specific overexpression of cyclin D1 did not cause hypoglycemia; in fact, glucose and insulin levels remained similar to those in the wild type." (PMID 26759123, 2016). "The purpose of this docking was to investigate whether the primary bioactive constituents of the compound played a role in hypoglycemia through the compound's key targets, which were CDK2, E2F1, CDKN1A, CDK1, and CCND1 and CCNB1." (PMID 36846049, 2023).
insulinoma (4 papers, 2009 to 2020). "A previous study reported dysregulation of epigenetic factors including genomic amplification of EZH2 and overexpression of EZH2 promoted CCND1-induced proliferation of insulinoma cells in human, whereas declined functions of these factors with aging were previously reported in mice." (PMID 33294783, 2020). "It has been reported that Sox6 inhibits cyclin D1 expression by interacting with β-catenin and HDAC1 in insulinoma INS-1E and NIH-3T3 cells and that down-regulation of cyclin D1 is important for cell cycle exit." (PMID 24040263, 2013).
malignant mesothelioma (4 papers, 2019 to 2024). A malignant neoplasm of the pleura or peritoneum, arising from mesothelial cells. "YAP/TAZ drives the transcription of key cell cycle genes, such as the cell cycle transcription factor forkhead box protein M1 (FOXM1) and its target CCND1 (encoding cyclin D1) in malignant mesothelioma cells." (PMID 38607003, 2024). "YAP also enhances malignant mesothelioma cell growth and survival via the upregulation of cyclin D1 (CCND1) and FOXM1 in cooperation with TEAD." (PMID 31100975, 2019). "Moreover, YAP has been shown to be able to directly induce the transcription of CCND1 and FoxM1 via the YAP-TEAD binding site in the FoxM1 promotor region in malignant mesothelioma cells." (PMID 30744076, 2019).
metastatic prostate carcinoma (4 papers, 2007 to 2021). A carcinoma that arises from the prostate gland and has spread to other anatomic sites. "Moreover, increased cyclin D1 is associated with increased cell growth and tumorigenicity in LNCaP cells as well as in metastatic prostate cancer." (PMID 33540707, 2021).
mucosal melanoma (4 papers, 2021 to 2025). A melanoma that arises from a mucosal site. "At present, some studies have found that mutations that activate SF3B1 and KIT, the deletion of CDKN2A, PTEN, or SPRED1, and the amplification of CDK4, TERT, KIT, MDM2, or CCND1 are common in mucosal melanoma." (PMID 38065883, 2023).
odontogenic cyst (4 papers, 2015 to 2024). A cyst in the jaw that arises from tissues of tooth development. "Key words:Keratin-producing odontogenic cyst, keratocyst, keratocystic odontogenic tumor, nevoid basal cell carcinoma syndrome, orthokeratinized odontogenic cyst, cyclin D1, immunohistochemistry." (PMID 25475773, 2015). "Accordingly, a recently published study quantified Cyclin D1 (CCD1) expression levels, a nuclear protein essential for cell cycle progression, in a series of keratin-producing odontogenic cysts." (PMID 27475699, 2016).
pancreatitis (4 papers, 2013 to 2023). Inflammation of the pancreas. "Analysis of miRs network and pancreatitis-associated genes provided potential therapeutic targets such as hsa-miR-15a (CCND1), hsa-miR-16 (CCND1)], hsa-miR-155 (CCND1/SMAD2), hsa-miR-375 (AKT2/CDK6) and hsa-miR-429 (CCND1)." (PMID 36674571, 2023). "Of particular note is the observation that the relative expression of BCL-6, a proto-oncogene known to suppress genes involved in cell cycle progression, particularly cyclin D1, and inflammation, was lower in ductal carcinomas compared with pancreatitis." (PMID 23737761, 2013).
periodontitis (4 papers, 2022 to 2025). An acute or chronic inflammatory process that affects the tissues that surround and support the teeth. "Our findings implicated CASP3 (odds ratio = 1.25004, 95% CI 1.09498-1.42706, p < 0.001) and CCND1 (odds ratio = 1.55479, 95% CI 1.33389-1.81227, p < 0.001) as being significantly associated with the progression of acute periodontitis." (PMID 41023518, 2025). "The relevant genes that were involved in the PI3K/AKT pathway activation observed in the T2DM-related periodontitis included those that affect apoptosis (e.g., FOXO1, BCL2, and growth differentiation factor 15 [GDF15]) and cell cycle passage (e.g., CDKN1B and CCND1)." (PMID 38241313, 2024). "The genes with the highest degrees in shared-DEminRNA-gene network included PTEN, CCND1, MDM2, SCD, and TNRC6A, and these may be important miRNA-deregulated mediators linking H. pylori infection and periodontitis." (PMID 35132337, 2022). "Conversely, periodontitis-negative bacteria did not alter tumor volume induced by SCC-7 in buccal mucosa but decreased angiogenesis and cyclin D1, while increasing γH2AX-positive cells, suggesting a protective role against tumor progression." (PMID 40924302, 2025).
plasmacytoma (4 papers, 2014 to 2024). Plasmacytoma is a localized mass of neoplastic monoclonal plasma cells that represents approximately 5% of all plasma cell neoplasms. "The strong cyclin D1 positivity is thus robust evidence for the presence of this translocation in our patient's plasmacytoma." (PMID 24715915, 2014). "The plasmacytoma stained strongly for the cell cycle regulator cyclin D1 on immunohistochemistry, while the original intravascular large cell lymphoma was negative, a disparity providing no support for clonal identity between the 2 neoplasms." (PMID 24715915, 2014). "Distinct from the secondary spinal plasmacytoma, the initial cerebral IV LBCL proved to be negative for cyclin D1 expression." (PMID 24715915, 2014).
polyp (4 papers, 2013 to 2023). A usually exophytic mass attached to the underlying tissue by a broad base or a thin stalk. "In a clinical trial, oral administration of BBR was also found to diminish the polyp size and reduce cyclin D1 expression in the polyp samples of patients with familial adenomatous polyposis patients." (PMID 31950049, 2019). "Oral administration of berberine significantly reduced the familial adenomatous polyposis patients’ polyp size along with the inhibition of cyclin D1 expression in polyp samples." (PMID 31417401, 2019). "Suppression of c-Myc and Cyclin D1 observed in the aspirin-treated group may have contributed to inhibition of the growth of polyp size especially in the case of small polyps." (PMID 38072949, 2023).
pterygium (4 papers, 2009 to 2017). A wedge-shaped fibrovascular lesion arising from the bulbar conjunctiva and extending to the cornea. "Studies of cyclin D1 expression in pterygium are very few in number." (PMID 21179427, 2010). "To test these hypotheses, we analyzed both the expression of β-catenin and cyclin D1 in pterygium and the relationship between β-catenin protein localization and cyclin D1 protein expression." (PMID 21179427, 2010). "In the pterygium group, cyclin D1 proteins were detected in 60 (40.0%) patients." (PMID 21179427, 2010). "Correlation of cyclin D1 protein expression and clinical parameters of pterygium." (PMID 21179427, 2010). "Therefore, we considered that the activation of cyclin D1 by β-catenin may be involved in pterygium proliferation." (PMID 21179427, 2010). "Therefore, we suggested that the cyclin D1 protein may be involved in pterygium progression." (PMID 21179427, 2010).
schwannoma (4 papers, 2020 to 2025). A benign, usually encapsulated slow growing tumor composed of Schwann cells. "Canonical Wnt/β-catenin activation in Schwann cells has been shown to drive schwannoma genesis, accompanied by upregulation of Wnt target genes such as c-Myc and cyclin D1." (PMID 41300852, 2025). "PAK2 modulates STAT3 signaling to enhance cyclin D1 expression; activates Wnt/β-catenin signaling in Schwannoma cells." (PMID 39769207, 2024). "In addition, one investigation highlighted the pivotal role of PAK2 in the activation of Wnt/β-catenin signaling in Schwannoma cells, with depletion of PAK2 resulting in diminished levels of active β-catenin, c-Myc, and cyclin D1." (PMID 39769207, 2024). "We found that upregulated genes PIK3CG, CSF1R, SPP1, and CCND1 and downregulated genes EGFR and VWF were significantly enriched in PI3K-Akt signaling pathway involved in VSs development, which can increase schwannoma cell proliferation, survival, and cell-matrix adhesion acting." (PMID 32733557, 2020).
Sepsis (4 papers, 2014 to 2024). Sepsis is defined as life-threatening organ dysfunction caused by a dysregulated host response to infection. "We also found that the increased rate of CD4 T cell proliferation in sepsis following treatment with ghrelin was directly linked with the increased expression of cell cycle positive regulators cyclin D1 and cyclin B1 and decreased expression of the cell cycle negative regulator p57." (PMID 30052667, 2018). "LncRNA Rian has been reported to reduce sepsis in CMs and attenuate myocardial ischemia–reperfusion damage by regulating the miR-17-5p/CCND1 axis." (PMID 39125754, 2024). "The most striking finding of this study was the effect of colistin on cyclin D1 levels, which decreased in both sepsis-free and septic animals, with a more pronounced effect in septic animals." (PMID 37370376, 2023). "Vasoconstriction elevated colistin effects on cyclin D1 levels in both sepsis-free (*** p< 0.001, colistin-treated vs. colistin/AVP/NA-treated animals) and septic animals (*** p < 0.001, LPS- and colistin-treated vs. LPS-and colistin/AVP/NA-treated animals)." (PMID 37370376, 2023). "On the other hand, colistin decreased skeletal muscle cyclin D1 levels both in sepsis-free (*** p < 0.001, colistin-treated vs. control animals) and septic animals (* p< 0.05, LPS-treated vs. LPS- and colistin-treated animals)." (PMID 37370376, 2023). "The expression of cyclin D1 and B1 was significantly increased, while the expression of p57 was decreased in ghrelin-treated mice compared to vehicle-treated mice in sepsis." (PMID 30052667, 2018). "Cyclin D1 was markedly decreased after sepsis with the lowest levels at day 3 after CLP in our study." (PMID 30052667, 2018). "We examined splenic levels of cyclin D1 and D2 after sepsis." (PMID 30052667, 2018). "We noticed significant decrease in the expression of cyclin D1 in spleen tissues by 26% at day 1 after CLP, while its expression was further decreased by 42% and 50% at day 2 and 3 after sepsis as compared to sham-operated mice, respectively." (PMID 30052667, 2018). "The increased expression of cyclin D1, VEGF, and MMP7 in our study supports the importance of Wnt signaling in perpetuating lung inflammation and provides insights into the early development of a pro-fibrotic response during sepsis-induced ARDS." (PMID 25331176, 2014).
soft tissue sarcoma (4 papers, 2013 to 2025). A malignant neoplasm arising from muscle tissue, adipose tissue, blood vessels, fibrous tissue, or other supportive tissues excluding the bones. "Downregulation of CCND1 and CDC25A genes was also observed in soft tissue sarcoma cell lines." (PMID 33923996, 2021).
Stroke (4 papers, 2018 to 2025). Sudden impairment of blood flow to a part of the brain due to occlusion or rupture of an artery to the brain. "Moreover, stroke-induced downregulation of downstream neurogenic markers (Cyclin D1 and Nestin) in the right hippocampus was ameliorated by BHD." (PMID 40973940, 2025). "In addition, an increase in cyclin D1 immunoreactivity has also been detected in human stroke brains." (PMID 36159397, 2022). "The miR-17-5p may function by targeting hub genes like “CCND1, E2F2, UBE3C, RBL2, and ITCH”, while miR-15a-5p may contribute in identifying certain subtype of stroke by regulating E2F3, UBE4A, and EIF2C4." (PMID 30627556, 2018). "Therefore, we suppose that CAMTA1 could regulate cyclin D1, and through this intermediate CAMTA1 could play a role in stroke." (PMID 36159397, 2022).
T-cell acute lymphoblastic leukemia (4 papers, 2018 to 2023). Acute lymphoblastic leukemia of T-cell origin. "In patients with T-cell acute lymphoblastic leukemia (T-ALL), HIF-1α is overexpressed, and HIF-1α can promote the activation of Notch1 signaling, increase the expression of cyclin D1, CDK2, p21, MMP2, and MMP9 proteins, thereby leading to cell proliferation, invasion, and resistance." (PMID 35684364, 2022).
tongue cancer (4 papers, 2014 to 2021). A malignant neoplasm affecting the tongue. "We have also examined the role of AP-1 downstream target genes Bcl-2, MMP-9 and Cyclin D1 in tongue cancer." (PMID 26581505, 2015). "In order to examine the effect of Fra-2 silencing on AP-1 target genes associated with aggressive tumorigenesis, we checked the expression of Bcl-2, MMP-9 and cyclin D1 in siRNA treated tongue cancer cell lines." (PMID 26581505, 2015). "We observed significantly a higher expression of MMP-9, cyclin D1 and Bcl-2 genes in majority of tongue cancer cases and cancer cell lines particularly in HPV−ve cases that show aggressive tumor and worst prognosis." (PMID 26581505, 2015). "As high as 80% (40/50; P = 0.0001) of tongue cancer cases showed strong expression of MMP-9, 68% (34/50; p = 0.06) for Bcl-2 and 78% (39/50; P = 0.0001) for cyclin D1 genes." (PMID 26581505, 2015).
transitional cell carcinoma (4 papers, 1997 to 2023). A malignant neoplasm arising from the transitional epithelium, usually affecting the urinary bladder, ureter, or renal pelvis. "Of patients who developed ⩾pT2, two out of 15 (13.3%) had amplification of c-myc, both in ⩾pT2, five out of 15 (33.3%) had CCND1 amplification, two in pTa/pT1 tumours, three in ⩾pT2 transitional cell carcinomas." (PMID 12237776, 2002). "We analysed the expression of cyclin D1 in 75 patients with transitional cell carcinoma (TCC) to investigate the possible relationship between its expression and clinical outcome as well as histopathological findings using the immunohistochemical method." (PMID 9192983, 1997).
uterine sarcomas (4 papers, 2014 to 2023). "The overexpression of cyclin D1 has been observed in various types of human malignancies, including uterine sarcomas." (PMID 35876683, 2023). "There is limited data regarding cyclin D1 immunoreactivity in uterine sarcomas." (PMID 35876683, 2023). "Among uterine sarcomas, cyclin D1 is strongly and uniquely overexpressed in YWHAE-NUTM2 HG-ESS9." (PMID 33947829, 2021).
cervical squamous cell carcinoma (3 papers, 2022 to 2024). A squamous cell carcinoma arising from the cervical epithelium. "GSK3β was involved in the development of cervical squamous cell carcinoma by negatively regulating the nuclear accumulation of Cyclin D1, while p21 and p27 jointly stabilize the Cyclin D1 protein by inhibiting its nuclear export." (PMID 37951919, 2023).
cholestasis (3 papers, 2016 to 2017). Impairment of the bile flow caused by obstruction within the liver, or outside the liver in the bile duct system. "In cholestasis, cyclin D1 overexpression has been implicated in toxic bile acid-induced Bax translocation, cytochrome c release and apoptosis of hepatocytes." (PMID 27490694, 2016). "The inhibition of cyclin D1 expression by SR 11302 in our experimental model of cholestasis increased the cell doubling time (decreasing cell metabolic activity) but it significantly reduced the caspase-3 associated activity." (PMID 27490694, 2016). "Our data provide direct evidence for the involvement of AP-1 in the NOS-3 expression regulation during cholestasis and define a critical role for NOS-3 in regulating the expression of cyclin D1 during the cell damage induced by bile acids." (PMID 27490694, 2016). "In a mouse model of chronic cholestasis, developed to study the mechanisms by which cholestasis contributes to biliary carcinogenesis, MYC was upregulated during CCA progression and resulted in induction of cyclin D1, a protein that contributes to dedifferentiation and cell proliferation in CCA." (PMID 27127503, 2016).